ZNF532 (zinc finger protein 532)
Description:
May be involved in transcriptional regulation.
Synonyms: FLJ10697
Tractability: PROTAC: UniProt records ubiquitination sites on it; ubiquitination databases record sites on it.
Gene: Protein-coding gene on chromosome 18 (58,862,600 to 58,986,480, forward strand). Ensembl gene ENSG00000074657.
Subcellular location: Nucleus
Subcellular location (Human Protein Atlas): Nucleoplasm; Golgi apparatus
Pathways (Reactome):
Chromatin organization: Interaction of NuRD complexes with transcription factors
Gene Ontology:
Molecular function: DNA-binding transcription factor activity
Biological process: regulation of DNA-templated transcription
Cellular component: nucleoplasm; nucleus
Genetic constraint (gnomAD): Loss-of-function variants: 19 observed, 90.72 expected, observed/expected ratio (o/e) 0.21, 90% interval 0.14 to 0.31. The upper end of that interval is the gene's LOEUF score, 0.31, which puts it in group 1 of 6, group 1 being the genes least tolerant of losing a copy. Missense variants: 1,132 observed, 1,703.5 expected, observed/expected ratio (o/e) 0.66, 90% interval 0.63 to 0.7. Synonymous variants: 606 observed, 670.99 expected, observed/expected ratio (o/e) 0.9, 90% interval 0.84 to 0.97.
Homologues: Orthologues: macaque ZNF532 (99% identical), guinea pig ZNF532 (96% identical), dog ZNF532 (94% identical), pig ZNF532 (94% identical), rabbit ZNF532 (94% identical), rat Zfp532 (92% identical), mouse Zfp532 (91% identical), tropical clawed frog znf532 (74% identical), zebrafish znf532 (67% identical), Caenorhabditis elegans F57C9.4 (10% identical), Caenorhabditis elegans K09F6.6 (7% identical), Drosophila melanogaster CG9609 (7% identical), and 6 more. Paralogues in human: ZNF200 (8% identical), KRABD1 (3% identical).
Diseases named in the same sentence as ZNF532 in open-access papers:
ZNF532 is named in the same sentence as 22 diseases in open-access papers, as found by Europe PMC text mining. Sharing a sentence is not in itself a finding about the gene and the disease. The quoted sentences say what the papers report.
colorectal cancer (2 papers, 2020 to 2023). A primary or metastatic malignant neoplasm that affects the colon or rectum. "The expression levels of VSIG4, ZNF532, MEIS2, and CXCL13 were downregulated, while CXCL10 was elevated between colorectal cancer and normal tissues." (PMID 36909170, 2023).
ovarian carcinoma (2 papers, 2023 to 2024). A malignant neoplasm originating from the surface ovarian epithelium. "The prognostic information of our five hub genes were determined using the KM plotter (SCN2A, ELAVL2, BCL2, MAF, and ZNF532,) to confirm the association between patterns of expression and metastasis risk in ovarian cancer patients." (PMID 38654363, 2024). "All the genes found are significant and play important roles in ovarian cancer and various other cancers, but the role of ZNF532 in ovarian cancer is yet to be discovered." (PMID 36829472, 2023). "The previous study observed a downregulation of the genes SCN2A, ELAVL2, ZNF532, MAF and BCL2 which were identified in ovarian cancer." (PMID 38654363, 2024).
diabetes (1 paper, 2022). "For example, circular RNA HIPK3 (circHIPK3) 14, circular RNA PWWP2A (cPWWP2A) 15, and circular RNA ZNF532 (circRNA-ZNF532) 16 have been discovered to play important roles in the development of diabetes-induced retinal vascular leakage." (PMID 36263181, 2022).
laryngeal squamous cell carcinoma (1 paper, 2023). A squamous cell carcinoma that arises from the larynx. "At an epithelial cellular level, activation of ZNF532 could promote the epithelial-to-mesenchymal transition in laryngeal squamous cell carcinoma cells." (PMID 37144239, 2023).
male infertility (1 paper, 2025). The inability of the male to effect fertilization of an ovum after a specified period of unprotected intercourse. "In the present study, we identified a panel of circular RNAs associated with male infertility, including hsa-SAP130_0002, hsa-TRPC1_0001, hsa-FBRS_0001, hsa-ACACA_0025, hsa-UTRN_0042, and hsa-ZNF532_0023, whose parental genes are predominantly expressed in the testes or prostate." (PMID 40391511, 2025).
osteosarcoma (1 paper, 2023). A usually aggressive malignant bone-forming mesenchymal neoplasm, predominantly affecting adolescents and young adults. "With respect to ZNF532 and COLEC12 in the model, elevated expression of COLEC12 had a worse prognostic outcome and increased inflammation in osteosarcoma." (PMID 37144239, 2023).
pancreatic ductal adenocarcinoma (1 paper, 2022). An infiltrating adenocarcinoma that arises from the epithelial cells of the pancreas. "ZNF532 has been linked to the prognosis of pancreatic ductal adenocarcinoma." (PMID 35847938, 2022).
cancer (3 papers, 2020 to 2023). A tumor composed of atypical neoplastic, often pleomorphic cells that invade other tissues. "ZNF532 encodes a protein that prominently interacts with the BRD4-NUT interacting fusion oncoprotein in the chromatin of NUT midline carcinoma cells and drives oncogenesis by propagating the oncogenic chromatin complex." (PMID 32644941, 2020). "The role of TULP4, MKLN1, and ZNF532 in cancer is largely unknown." (PMID 35078526, 2022).
tumor (3 papers, 2020 to 2023). "In the risk model, CAF abundances in tumor microenvironment were positively connected with the risk score and the levels of ZNF532 and COLEC12." (PMID 37144239, 2023). "The expression of ANGPT2, GLDN, and ZNF532 was significantly higher in the 268 HCC tumor tissues of the GSE25097 dataset compared to the 243 non-tumor liver tissue samples (p < 0.001)." (PMID 32644941, 2020). "Nevertheless, the expression of ANGPT2, EMCN and ZNF532 genes was significantly higher in the HCC tumor samples compared to the normal liver tissue samples." (PMID 32644941, 2020). "In conclusion, higher infiltration of stromal CAFs in tumor microenvironment was associated with poor prognosis in CRC, and ZNF532 and COLEC12 could be as novel prognostic CAF biomarkers by producing the prediction model." (PMID 37144239, 2023). "We also found that the expression of these 5 genes, namely, ANGPT2, EMCN, GLDN, USHBP1 and ZNF532, was significantly upregulated in HCC tumor tissues compared to the adjacent normal liver tissues in the TCGA and ICGC datasets." (PMID 32644941, 2020). "Overall, the predictive model composed of ZNF532 and COLEC12 may predict the state of CAF infiltrations in tumor microenvironment." (PMID 37144239, 2023). "In addition, ZNF532 was distributed in endothelial cells, while COLEC12 also belonged to macrophage, speculating CAF signature affecting tumor progression by regulating tumor matrix formation and immune infiltration of CRC." (PMID 37144239, 2023). "Furthermore, ZNF532 was mainly distributed in cluster 6, and COLEC12 was mainly distributed in cluster 5, which that suggested cluster 6 and cluster 5 in fibroblasts were mainly involved in tumor progression and immunotherapy of CRC." (PMID 37144239, 2023). "We found two deleted regions shared by both tumor types in three out of the four cell lines H23R, A2780R, and OVCAR3R, but not in H460 cells, located on 18q21.2–18q21.31 and 18q21.32, affecting the genes RAB27B, CCDC68, TCF4, TXNL1, WDR7, and BOD1P; and genes ZNF532, SEC11C, GRP, respectively." (PMID 32224864, 2020).
ZNF532 also shares sentences with these, for which no sentence is quoted: bladder cancer (1 paper); breast carcinoma (1); cervical cancer (1); endometrioid endometrial adenocarcinoma (1); esophageal cancer (1); gastric cancer (1); head and neck cancer (1); kidney cancer (1); leukemia (1); liver cancer (1); lung carcinoma (1); lymphoma (1); nut midline carcinoma (1).